EZH2 (enhancer of zeste 2 polycomb repressive complex 2 subunit)
Diseases named in the same sentence as EZH2 in open-access papers (continued):
Sharing a sentence is not in itself a finding about the gene and the disease.
tumor (continued). "EZH2 is highly expressed in various human malignancies and regulates tumor progression." (PMID 35538070, 2022). "In this way, EZH2 is generally thought to remove the barriers against tumor growth and progression." (PMID 36230683, 2022). "EZH2 is a classic epigenetic protein that silences tumor suppressors through H3K27me313." (PMID 35538070, 2022). "Furthermore, upregulation of EZH2 in MEG3‐overexpressing cells decreased the anti‐tumour effect of MEG3." (PMID 35257481, 2022). "Moreover, several potential molecular mechanisms have revealed that EZH2 enrichment shapes the immunosuppressive tumor microenvironment." (PMID 36713412, 2022). "Moreover, ELFN1-AS1/EZH2/DNMT3a affected tumor growth and oxaliplatin resistance by regulating MEIS1-FEN1." (PMID 35351858, 2022). "Similarly, EZH2 is another ideal candidate for tumor gene therapy, which is overexpressed in many tumors." (PMID 35874843, 2022). "So far, a clear understanding of what determines whether EZH2 acts oncogenic or tumor suppressive is missing." (PMID 34762160, 2022). "Furthermore, it has been demonstrated that EZH2 is involved in innate and adaptative immune response in cancer, promoting tumor development through a cell-extrinsic mechanism that involves the inhibition of the antitumor activity of NK cells." (PMID 36430394, 2022). "TCGA-based bioinformatics analysis was carried out; as a result, SUV39H2, together with additional new genes (DNMT3B, SUV39H1, AURKB, and EZH2) was remarkably upregulated within TN disorders, which was positively related to Ki67 upregulation, tumor grade, and TN status." (PMID 36188615, 2022). "After propofol treatment, the palmitoylation level of EZH2 in tumor stem cells increased, which may be related to the increased palmitoyltransferase ZDHHC5 expression." (PMID 35927718, 2022). "However, EZH2 and H3K27me3 have been linked to poor prognosis in many solid human cancers, emphasizing the important roles of EZH2/H3K27me3 in inhibiting the expression of different tumor suppressor genes which are the common EZH2 targets identified in cancer." (PMID 36230683, 2022). "The circ_ANKIB1, miR-26b-5p, and EZH2 expression in OS tissues and corresponding para-cancerous tissues were determined, and the results confirmed an increased circ_ANKIB1 expression in the tumor compared to the normal tissues." (PMID 35264070, 2022). "EZH2 acts both tumor-promoter and tumor-suppressor roles in certain type of cancer." (PMID 36263120, 2022). "Along the same evidential lines, EZH2 inhibition reduces tumor growth rates in vivo." (PMID 35955891, 2022). "Importantly, upon EZH2 depletion in PDAC models with EZH2-disentangled, constitutive NFATc1 activation strongly abrogated the tumor-promoting activities of the transcription factor, both in vitro and in vivo." (PMID 34943970, 2021). "Furthermore, PDX tumours overexpressing EZH2 appeared to gain resistance to infigratinib and showed a better response to varlitinib." (PMID 34156519, 2021). "By contrast, studies have shown that HIF-1α can upregulate EZH2 expression in tumor models." (PMID 34737746, 2021). "Moreover, an evidence suggested that EZH2 mediates tumor progressions through regulating the expression levels of multiple genes, including KLF2, DKK-1, CDKN1C, ZEB1, ACE2, Robo4, P4HA1, and DUXAP8." (PMID 34257531, 2021). "Our data suggest that that MiR-101 could be involved in the regulation of these pathways, as it has been shown to directly target the histone methyltransferase enhancer of zeste homologue 2 (EZH2), which could promote tumor proliferation and invasion." (PMID 34513655, 2021).
tumor (continued). "We demonstrated that Ili-A could be a novel EZH2 antagonist that exerts anti-tumor effects against CRPC in vitro and in vivo and capable of enhance the anticancer activity of enzalutamide in CRPC cancer models." (PMID 34776951, 2021). "We also assessed EZH2 expression by molecularly characterized tumor-immune phenotypes." (PMID 34140011, 2021). "Furthermore, studies have revealed that the canonical and noncanonical functions of EZH2 are not mutually exclusive but coexist in the same cell, pinpointing the cell-context-dependent and multifaceted effects of EZH2 on tumor progression." (PMID 33803922, 2021). "Currently, research has led to the knowledge of the function of EZH2 in tumor progression." (PMID 34372908, 2021). "Indeed, we observe this in other PDX lines, where the inhibition of both ErbB and FGFR abolished the EZH2 expression and provided a longer lasting tumour suppression." (PMID 34156519, 2021). "The inhibition of EZH2 activity may slow tumor growth by upregulating tumor suppressor gene expression." (PMID 33403469, 2021). "And the posttranslational modifications of EZH2 are essential to improve its protein stability that related to the function of tumor cells and tumor metastasis, which could further lead to the accumulation of EZH2 and the occurrence of cancers." (PMID 34737956, 2021). "Furthermore, in keeping with the effect of EZH2 inhibition in tumor cells, Mo-TAMs from EPZ-6438-treated MCS showed a consistent enhanced expression of monocyte chemoattractants CCL2 and VEGF but not Th1-recruiting chemokines (CXCL9, CXCL10, CXCL11)." (PMID 33922336, 2021). "Moreover, we found that Ki67 expression in tumours (a cell proliferation marker) was much higher in the EZH2-WT group than in the other two groups." (PMID 34775498, 2021). "Furthermore, EZH2 expression is generally correlated with the development of a metastatic type of tumor and often behaves as a molecular biomarker of poor prognosis." (PMID 34372908, 2021). "In summary, EZH2 is related to different kinds of neoplasms, which was abnormally expressed and could serve as a therapeutic target." (PMID 34737956, 2021). "Therefore, this target is gradually becoming one of the research hot spots of tumor pathogenesis, and the inhibitors of the EZH2 enzyme are expected to become new antitumor drugs." (PMID 34737956, 2021). "Based on the results of functional analyses, we firstly hypothesized that CCNB1 and EZH2 could be involved in chemoresistance through changing the tumor immune microenvironment." (PMID 34077304, 2021). "The EZH2 protein was low expressed in normal tissues and moderately expressed in tumor tissues." (PMID 33758106, 2021). "Lower expression of UTX may result in an imbalance status, reduction of inhibiting H3K27 methylation by UTX and activation of H3K27 methylation by EZH2, contributing to tumor cell transcription and poor prognosis." (PMID 34465286, 2021). "Consequently, the anti-tumor activity of T cells was restored in tumors treated with the EZH2 inhibitor." (PMID 33859645, 2021). "Additionally, in tumor-associated endothelial cells, VEGF is involved in mir-101 downregulation and consequently, the EZH2 expression increases promoting angiogenesis." (PMID 33602320, 2021). "Taken together, these results show that the combined use of EZH1/2 dual inhibitor may enhance the anti-tumor effects of sorafenib by canceling sorafenib-induced activation of EZH2 and additional inhibition of EZH1." (PMID 34725436, 2021). "Similarly, treatment of Rip1TAG2 mice, a transgenic PanNEC mouse model, with EZH2 inhibitor reduced tumor burden." (PMID 34638497, 2021). "In addition, in two murine HNSCC transplantable cell line models, we confirmed in vivo upregulation of tumor cell antigen presentation induced by EZH2 inhibition." (PMID 33403469, 2021). "However, understanding the overall impact of EZH2 inhibition on antitumor immunity requires consideration of its pleiotropic effects on different types of immune and tumor cells." (PMID 33922336, 2021).
tumor (continued). "Further results of ChIP assays revealed that SNHG22 could recruit EZH2 to the promoter regions of multiple tumor suppressor genes (E-cadherin, EAF2, ADRB2, rap1GAP and RUNX3), and modulating H3K27me3 levels to repress their transcription." (PMID 34663788, 2021). "Therefore, EZH2is are insufficient to inhibit cell growth and induce apoptosis in BC cells, whereas silencing of EZH2 by RNA interference effectively suppress tumor growth." (PMID 34595180, 2021). "In addition, combinatorial therapy of EZH2 inhibition and anti-PD-1 significantly suppressed tumor growth in an anti-PD-1 resistant model of HNSCC." (PMID 34680389, 2021). "More recently, overexpression of enhancer of zeste homolog 2 (EZH2), an H3K27-specific histone methyltransferase with an oncogenic role in NKTCL, was shown to be significantly associated with higher tumor cell proliferation, advanced stage, and higher risk of death." (PMID 34440582, 2021). "Our results showed that tumours of the EZH2-WT groups were much larger and heavier than those of the vector group or the EZH2-R342K group; nevertheless, the size and weight of tumours in the EZH2-R342K group and the vector group showed little change." (PMID 34775498, 2021). "ZMYND8 Promotes Tumor Migration and Invasion via Interacting with EZH2 in ccRCC Cells." (PMID 33593912, 2021). "Other studies have shown that induction of EZH2 in benign BrafV600E- or NrasQ61K-expressing melanocytes facilitates tumor metastasis and invasiveness by silencing genes relevant for cell surface organelle primary cilium integrity and by activating Wnt/β-catenin oncogenic signaling." (PMID 34575678, 2021). "Overexpression of DNA repair proteins such as PARP1, checkpoint kinase 1 (Chk1), and enhancer of zeste two polycomb repressive complex two subunit (EZH2) are independent of DNA-level mutations, but significantly contribute to tumor growth." (PMID 34531756, 2021). "In 79% of PanNENs (n = 136/172), the percentage of tumor cells positive for EZH2 was ≤3%." (PMID 34638497, 2021). "Tumor microenvironment-mediated upregulation of EZH2 has been reported in various types of NHL." (PMID 34200679, 2021). "The percentage of EZH2-positive tumor cells was scored for each patient." (PMID 34638497, 2021). "Thus, EZH2 can have either an oncogenic or tumor suppressor function, depending on the cellular context." (PMID 34001289, 2021). "Interestingly, the colony formation capacity of pG-2 cells seeded at low cell density was strongly improved upon EZH2 inhibition, suggesting increased tumor-initiating properties." (PMID 34845197, 2021). "As the catalytic subunit of PRC2, EZH2 has an essential role in tumor progression." (PMID 33966039, 2021). "Previous studies have shown that lncRNA could form an RNA–protein complex to modulate gene transcription in tumor biology, of which the binding of lncRNA with several epigenetic modifiers such as EZH2 is most frequently reported." (PMID 34545072, 2021). "Moreover, we determine at the single-cell level how inhibition of EZH2 - the top upregulated gene along the trajectory – reverts tumor progression and macrophage polarization." (PMID 34857732, 2021). "Taken together, these results demonstrate that TCF3 is a direct target of EZH2, which may act as a tumor suppressor to inhibit proliferation of EC cells." (PMID 34175897, 2021). "EZH2 is a histone methylation enzyme that plays an important role in tumor invasion and metastasis." (PMID 34409953, 2021). "Therefore, the discovery of EZH2-regulated signaling pathways that promote cancer cell survival will help set up novel tumor treatment strategies." (PMID 33794893, 2021). "However, knocking down EZH2 or DDX5 in tumor cells increased IκBα levels and decreased the nuclear levels of NF-κB and p-NF-κB." (PMID 33754075, 2021).
tumor (continued). "In recent years, the tumor-suppressive roles of EZH2 were also identified." (PMID 34381492, 2021). "They showed that EZH2 inhibition in EwS cells improved anti-GD2 CAR T cell anti-tumor activity." (PMID 34207884, 2021). "Research also reported that EZH2 may promote tumor invasion and metastasis by downregulating downstream targets such as E-cadherin and vascular endothelial growth factor (VEGF)-A." (PMID 34737956, 2021). "Thus, EZH2 was capable of accelerating tumorigenesis as well as the malignant progression of tumor cells via the stimulation of the Warburg effect." (PMID 34745848, 2021). "This study provided evidence for the targeted treatment of OS regarding EZH2 and may have the potential to provide better methods for tumor treatment." (PMID 34737956, 2021). "The novelty of our work is that we firstly address the correlation between CCNB1, EZH2, and tumor immune microenvironment in docetaxel resistant PCa, and further investigate the relationship between immune cell infiltration and the expression of these two prognostic hub genes." (PMID 34077304, 2021). "In support of this, we found that EZH2 inhibition in Rip1TAG2 mice reduced tumor burden." (PMID 34638497, 2021). "EZH2 has tumor-suppressive functions affecting tumor cell proliferation, invasion, or metastasis." (PMID 33791221, 2021). "Although EZH2 was thought to be an oncogene, deletion of EZH2 in mouse and human group 3 cells by CRISPR/cas9 gene editing approaches have resulted in loss of PRC2 complex, accelerating tumor growth." (PMID 35054230, 2021). "CircGSK3B acts as a tumor suppressor, reducing EZH2 trans-inhibition and GC progression." (PMID 34666800, 2021). "In addition, using RNA pull-down followed MS assay, we found that SNHG22 directly bound to EZH2 (enhancer of zeste 2 polycomb repressive complex 2 subunit) to suppress the expression of tumor suppressor genes." (PMID 34663788, 2021). "Overexpression of EZH2 is closely related to tumour progression and poor prognosis." (PMID 33986254, 2021). "Taken together, our data here proved that SNHG6 could directly interact with EZH2 and repress the expression of tumor-suppressor genes through H3K27me3 histone methylation." (PMID 33431838, 2021). "Given that our results suggested an association between the levels of EZH2 and the expression of ErbB proteins in infigratinib-resistant tumours, we hypothesised that EZH2 plays a role in the regulation of FGFR/ErbB proteins." (PMID 34156519, 2021). "Similarly, downregulation of EZH2 expression in cancer cells can lead to growth arrest, reduced tumor growth, and reduced metastasis." (PMID 34367971, 2021). "We then investigated whether EZH2-overexpressing tumours are more resistant to infigratinib, and whether they are more sensitive to varlitinib." (PMID 34156519, 2021). "Therefore EZH2 inhibition can promote an anti-tumour response via increased T cell infiltration and activation, restoration of antigen presentation, and the reversal of T reg immunosuppressive function." (PMID 33937922, 2021). "In addition to E2F, several transcription factors with critical involvement in carcinogenesis and tumor progression control EZH2 transcription, such as MYC, NF-YA, STAT3, ETS, and ELK1." (PMID 34943970, 2021). "Inhibiting DNA methyltransferases (DNMTs) may avoid hypermethylation of CDH1 and tumor suppressors, while the inhibitory chromatin-modifying effects of EZH2 may represses PRC2 activity." (PMID 34946849, 2021). "Furthermore, ChIP assays revealed that SNHG22 knockdown remarkably decreased the binding of EZH2 to the promoter regions of these tumor suppressive genes." (PMID 34663788, 2021). "From these observations, it appears that there may be a close link between EZH2 and the activity of DNMTs in regulating tumor biological properties, including the response to immunotherapy in CM." (PMID 34575678, 2021).
tumor (continued). "Consistent with previous studies, the mRNA of enhancer of zeste homolog 2 (EZH2) was detected in bioengineered tumor-derived exosomes, at a level similar to the one of plasma samples from EwS patients, but at a higher level than in exosomes secreted from monolayer cell lines." (PMID 34604225, 2021). "This study highlighted that EZH2 may be important for tumor initiation and the progression of normal epithelium to hyperplasia." (PMID 33235291, 2021). "In addition, EZH2 expression in immune cells in the tumour microenvironment is reported to have a direct role in mediating the T cell reaction." (PMID 33277782, 2021). "The combination of HDAC inhibitor HBI8000 with EZH2 inhibitor SHR2554 exhibited dramatic anti-tumor activity in both mutant and wild-type DLBCL, which may become a potential therapeutic modality for the treatment of DLBCL patients." (PMID 34503063, 2021). "Moreover, we revealed that inhibition of EZH2 using the clinical trial drug CPI-1205 or metformin inhibited SI-NET tumor growth in vitro." (PMID 34815475, 2021). "Overall, 14 out of 15 G3 PanNENs showed positivity for EZH2 in >3% of tumor cells." (PMID 34638497, 2021). "Similarly, pharmacological or genetic disruption of EZH2 activity has been shown to enhance natural killer cell maturation and anti-tumour function, which are often repressed in cancer." (PMID 34439236, 2021). "Importantly, EZH2 has recently been shown to modulate the immune response to tumor cells by reducing their immunogenicity." (PMID 32303902, 2021). "PRADX, mainly located in the nucleus of tumor cells, could bind to EZH2 protein via the 5' terminal sequence." (PMID 33754075, 2021). "With NFATc1, we identified a previously unknown inducer of EZH2 expression in PDAC development and progression and demonstrated that the tumor-promoting transcription factor directly targets the EZH2 gene for transcriptional activation." (PMID 34943970, 2021). "EZH2 expression in RipTag2 tumors increased with tumor size and animal age, suggesting that EZH2 inhibition may affect growth of late-stage tumors with higher EZH2 expression rather than of early-stage and small tumors." (PMID 34638497, 2021). "In RCC cells, these results reported that EZH2 exerted tumor effects conversely with miR-101-3p." (PMID 34307682, 2021). "Both tumor-suppressive and oncogenic effects of EZH2 have been reported in human malignancies." (PMID 33499872, 2021). "There is also evidence for synergy between ONC201 and EZH2 inhibitors in a variety of tumor types and this may be relevant to SCLC." (PMID 34531756, 2021). "Tumor cells in the TME may negatively influence the immune system via EZH2, thus impairing immune cell function and achieving immune escape." (PMID 34737746, 2021). "Furthermore, 19 CDC73 alterations were observed in 18 (53%) PC samples —including four samples exhibiting tumor invasion into the adjacent tissue and three lesions—followed by alterations in EZH2 (n = 2, 6%) and HIC1 (n = 2, 6%)." (PMID 33778063, 2021). "To further evaluate whether EZH2 is involved in tumorigenicity of SI-NETs in vivo, we used a tumor xenograft mouse model." (PMID 34815475, 2021). "iPSC-derived PDAC organoids were used to gain clinically important insights into PDAC as they maintained tumor-specific traits, inter-patient variation in tumor histoarchitecture, and showed differential responses to EZH2 inhibition as a therapeutic approach against PDAC." (PMID 34299287, 2021). "EZH2 facilitates glucose metabolism in tumor cells in several ways." (PMID 34072826, 2021). "In this study, GNA002 significantly suppressed H3K27Me3 and effectively reactivated PRC2-silenced tumor suppressor genes, and could inhibit tumor growth in an EZH2-dependent manner." (PMID 34054126, 2021).